TOP2A (DNA topoisomerase II alpha)
Diseases named in the same sentence as TOP2A in open-access papers (continued):
Sharing a sentence is not in itself a finding about the gene and the disease.
cervical cancer (continued). "We analyzed the expression of five cellular markers and their relation to SIL and cervical cancer development, and found that TOP2A/MCM2 staining is the best biomarker for discriminating between cervical lesion types, followed by p16INK4a, cyclin-E, Ki-67, and telomerase." (PMID 33413211, 2021). "Furthermore, immunohistochemistry staining revealed that, among 145 patients seeking cervical cancer care, 103 (71.0%) and 61 (42.1%) strongly expressed p16 (p16+) and TOP2A (TOP2A++) proteins, respectively." (PMID 34705880, 2021). "Specifically, TOP2A, a promoter of epithelial-mesenchymal transition (EMT), has been associated with increased invasive properties of cancer cells, and has been suggested as a prognostic factor for cervical cancer." (PMID 35008799, 2021). "In a multivariate logistic regression model, the age-adjusted OR for predicting cervical cancer lesions were independently significant for p16/TOP2A biomarkers in archived FFPE cervical tissues [p16: OR = 1.142 (95% CI: 1.059–1.232, p<0.001) and TOP2A: OR = 1.046 (95% CI: 1.008–1.085, p = 0.015)]." (PMID 34705880, 2021). "TOP2A and Ki-67 antibodies may be used in combination for cervical cancer screening in immunocytochemistry assays." (PMID 27175798, 2016). "TOP2A and Ki-67 may be a useful antibody combination for cervical cancer screening in health services currently using only conventional cytology." (PMID 27175798, 2016). "Moreover, TOP2A may be utilized as a biomarker that indicates poor prognosis and may function as a treatment target for cervical cancer." (PMID 35409038, 2022). "It has been established that TOP2A and Ki-67 antibodies can be used to screen for cervical cancer in immunocytochemical examination of cervicovaginal smears; in cervical cancer, there is an increased expression of nuclear proteins Ki-67 and type IIa DNA topoisomerase (TOP2A)." (PMID 34830452, 2021). "A relationship between TOP2A (Topoisomerase IIA) and the emergence and progression of cervical cancer is widely acknowledged." (PMID 38730579, 2024). "The TOP2A, AURKA and CCNA2 in cervical cancer were significantly increased, while IVL, KRT1, and IGFBP5 were significantly decreased, compared with normal tissues, which was consistent with the screening results." (PMID 39060960, 2024). "TOP2A, AURKA and CCNA2 were overexpressed in cervical cancer, while IVL and IGFBP5 were low expression in cervical cancer." (PMID 39060960, 2024). "The expression of these hub genes were verified through TCGA, GEPIA, qRT-PCR, and immunohistochemistry, and it was found that TOP2A, AURKA as well as CCNA2 were overexpressed and IGFBP5 was low expression in cervical cancer." (PMID 39060960, 2024). "Inhibition of E2F1 results in decreased levels of TOP2A and BIRC5 and subsequent inhibition of migration and proliferation of cervical cancer cells." (PMID 37509353, 2023). "Several studies based on TCGA-CESC data have reported the relationship between TOP2A and RFC4 mRNA expression and the prognosis of cervical cancer." (PMID 36352434, 2022). "Due to limited resources, genotyping of HPV subtypes was not performed which could predict the risks of cervical cancer lesions and its precursors development in association with the expression of p16 and TOP2A biomarkers in the studied population, and Tanzanian population at large." (PMID 34705880, 2021). "The combination of TOP2A and MCM2 in the commercial assay ProExCTM is used for immunohistochemistry analysis in cervical cancer samples." (PMID 27175798, 2016). "The results showed that the expression of TOP2A, AURKA and CCNA2 were statistically increased in cervical cancer cell, while the expression of IGFPB5 was statistically decreased in cervical cancer cell, which was consistent with the results of GEO dataset and TCGA database." (PMID 39060960, 2024).
cervical cancer (continued). "Studies involving HPV-16 and HPV-18 gene expression in cancers of the cervix affected by HPV 16 and 18 show that CDKN2/p16INK4A of the minichromosome maintenance (MCM) gene family and TOP2A are up-regulated in cancer cervix along with the increased expression of proteins of HPV E6/E7 genes." (PMID 39483945, 2024). "It was found that TOP2A, AURKA, CCNA2 and IGFBP5 could be all potential tumor markers for cervical cancer." (PMID 39060960, 2024). "The outcomes of this assessment substantiated our preliminary observations, revealing the upregulation of RRM2 and VEGFA, alongside the downregulation of RFC4, EXO1, PCNA, TOP2A, and TYMS in cervical cancer tissues relative to normal cervical epithelial tissues." (PMID 38926832, 2024). "Although MAD2L1, TOP2A, AURKA, and ASPM were reported in various research findings, they may play a remarkable role in the survival of cervical cancer." (PMID 36723760, 2023). "Notably, the TOP2A/MCM2 combination was reported to be the best biomarker for discriminating between low- and high-grade squamous intraepithelial lesions for cervical cancer." (PMID 35884419, 2022). "Several histological studies have reported the application of most common cellular biomarkers, including Ki-67, cyclin-dependent kinase inhibitor (p16), and ProEx C [topoisomerase II-alpha (TOP2A) and minichromosomal maintenance-2 (MCM2)] in the early diagnosis of cervical cancer." (PMID 34705880, 2021). "Our study has highlighted that over-expression of TOP2A is related to the grade of cervical intraepithelial neoplasia but does not predict prognosis in cervical cancer." (PMID 34705880, 2021). "Our study not only provides single-cell and experimental evidence for the treatment of cervical cancer with FOXM1, but also suggests that there may be a potential connection between FOXM1 and TOP2A, but this hypothesis still needs to be verified experimentally." (PMID 40589640, 2025). "Explore the effect of HPV16 E6 on the expression of miR‐320a in cervical cancer, and verify whether HPV16 E6 regulates the downstream target gene TOP2A expression through miR‐320a, thereby affecting cervical cancer cell proliferation, apoptosis, migration, invasion, and EMT in vitro and in vivo." (PMID 38205938, 2024). "This study showed that TOP2A, AURKA, CCNA2 and IGFBP5 screened through bioinformatics analysis were significantly differentially expressed in cervical cancer samples compared with normal samples, which might be biomarkers of cervical cancer." (PMID 39060960, 2024). "However, interestingly, the TCGA database and GEPIA online website analysis showed that TOP2A, AURKA, CCNA2 and IVL were overexpressed and IGFBP5 was low expression in cervical cancer, and there was no statistical difference in the expression of KRT1 in cervical cancer tissue and normal tissue." (PMID 39060960, 2024).
colorectal cancer (26 papers, 2007 to 2025). A primary or metastatic malignant neoplasm that affects the colon or rectum. "Previous studies have found that the co-expression of FOXM1 and TOP2A is significantly associated with poor prognosis in patients with colorectal cancer, bladder cancer, etc." (PMID 40589640, 2025). "In addition, in colorectal cancer, high levels of TOP2A expression are associated with malignancy and poor prognosis." (PMID 41284119, 2025). "In summary, we identified CX258 as a promising candidate for colorectal cancer treatment by targeting the TOP2A/Wnt/β-catenin signaling pathway." (PMID 37048139, 2023). "Topoisomerase II alpha (TOP2A) is highly expressed in colorectal cancer and is involved in the regulation of cell proliferation, apoptosis, and invasion." (PMID 38102686, 2023). "These TOP2A alterations were independent predictive markers of topoisomerase inhibitor efficacy in colorectal cancer cells that closely represent rectal cancer signatures." (PMID 34771654, 2021). "Growing lines of evidence indicate that TOP2A is overexpressed in a variety of tumors, such as lung cancer, hepatocellular cancer, and colorectal cancer." (PMID 34021129, 2021). "In colorectal cancer, the protein expression level of TOP2A was related to aggressive tumor phenotypes and advanced tumor stages." (PMID 32153633, 2020). "An important gene, TOP2A, was obtained for 5-FU resistance of colorectal cancer by bioinformatics analysis." (PMID 31662984, 2019). "In colorectal cancer, protein expression level of TOP2A was related to aggressive tumor phenotype and advanced tumor stage." (PMID 29651323, 2018). "Real-time PCR showed that MCM2, RNASEH2A, and TOP2A were upregulated in colorectal cancer compared with adjacent mucosa samples (MCM2, P < 0.001; RNASEH2A, P < 0.001; TOP2A, P = 0.001)." (PMID 29651323, 2018). "Moreover, Copy Number Variations (CNVs) in TOP2A gene have been identified as biomarkers of colorectal cancer." (PMID 34249670, 2021). "In our research, we found that TOP2A expression was upregulated in colorectal cancer." (PMID 32153633, 2020). "TOP2A is highly expressed in esophageal, liver, gastric, breast, and colorectal cancers." (PMID 31816603, 2019). "In our research, we found that TOP2A mRNA expression level was upregulated in colorectal cancer." (PMID 29651323, 2018). "Our study confirmed that MCM2, RNASEH2A, and TOP2A were upregulated in colorectal cancer." (PMID 29651323, 2018). "This suggested that TOP2A might be a key gene for 5-FU resistance of colorectal cancer." (PMID 31662984, 2019). "Besides TOP2α, topoisomerase-I, another protein from the topoisomerase family, has also been observed to be overexpressed in the tumor recurrences of patients with colorectal cancer who had received 5-FU-based adjuvant chemotherapy." (PMID 31662984, 2019). "Increased expression of TOP2A has been previously associated with poor cancer-specific survival in MPNSTs, whereas increased expression of ETV4, a member of the Ets family of transcription factors, has been associated with shorter patient survival in colorectal cancer and gastric cancer." (PMID 18522746, 2008). "For example, high copy numbers of ERBB2, TOP2A, CCND1, EGFR and MYC are observed in many colorectal cancers." (PMID 31009485, 2019). "These experiments confirmed that sites highly enriched in SOX9 binding overlap the NF-YA binding sites around the TSSs (within 500 bp of TSSs) of TOP2A, CCNB1, CCNB2 and CDK1 in colorectal cancer cells." (PMID 26040697, 2015). "TOP2A and CDNK3 have been screened to be involved in colorectal cancer progression." (PMID 38661103, 2024).
liver cancer (26 papers, 2018 to 2025). An epithelial or non-epithelial malignant neoplasm that arises from the liver. "Aberrant overexpression of TOP2A has been widely reported in multiple cancers, such as liver cancer and gastric cancer, where it is linked to aggressive tumor behavior and poor prognosis." (PMID 40765849, 2025). "Overexpression of TOP2A is observed in multiple types of cancer, such as lung, breast, and liver cancer, and it is linked to tumor progression, chemoresistance, and resistance to radiotherapy." (PMID 40290723, 2025). "Taken together, our results strongly indicated that liver cancer patients with an upregulated level of TOP2A, RRM2, NEK2, CDK1, and CCNB1 were associated with poor prognosis." (PMID 34681056, 2021). "The expression of TOP2A is associated with advanced histological grade in liver cancer." (PMID 39764737, 2025). "Subsequently, we analyzed the H3K27me3 occupying region in TOP2A gene based on H3K27me3 methylation-related chromatin immunoprecipitation (ChIP)-seq data from the Cistrome database for HepG2 liver cancer cell lines." (PMID 40271060, 2025). "Firstly, we analyzed gene expression of TOP2A in a normal liver cell line (LO-2) and four liver cancer cell lines (HepG2, Hep3B, HCCLM3, and MHCC97H)." (PMID 37980167, 2023). "The results observed by immunohistochemistry are consistent with the results we obtained in the HPA database, indicating that TOP2A can be used as a biomarker and potential prognostic value for liver cancer." (PMID 35033076, 2022). "The study also analyzed HCA data from 442 TCGA cases, PanCancer Altas, and 372 cases of TCGA, Firehose Legacy, and showed that liver cancer CNAs were closely related to top2A expression levels (single-factor variance analysis, p < 0.05)." (PMID 35033076, 2022). "Online survival analysis results show that the diagram below high TOP2A genes in liver cancer cells express the survival time of less than its survival rate in lower expression of liver cancer." (PMID 35033076, 2022). "Taken together, our results suggest TOP2A, RRM2, NEK2, CDK1, and CCNB1 as HCC-associated hub genes that can serve as potential prognostic biomarkers in liver cancer." (PMID 34681056, 2021). "DNA topoisomerase II alpha (TOP2A) is abundantly expressed in testis, lymph node tissues, and a variety of tumor tissues, including liver cancer." (PMID 33133125, 2020). "Moreover, the clinical data analysis showed that EZH2 was positively correlated with TOP2A, which was significantly increased in liver cancer." (PMID 40271060, 2025). "Therefore, it can be shown that the survival rate of liver cancer patients is affected by the expression of TOP2A." (PMID 35033076, 2022). "The aberrant expression of TOP2A is intimately associated with the proliferation, motility, invasion, and epithelial–mesenchymal transition (EMT) events of liver cancer, as well as the poor prognosis of patients with liver cancer, and indicates a possible therapeutic target for liver cancer." (PMID 38806610, 2024). "However, previous results show that TOP2A is involved in the development of liver cancer." (PMID 37383715, 2023). "Meanwhile, immunohistochemical results of AURKA, CCNB1, CDC20 and TOP2A were found through the HPA database, which also confirmed that there were significant differences between liver cancer tissues and normal adjacent tissues." (PMID 39537209, 2024). "TOP2A, CENPF, ACSL4, SPARC, and COL4A5 were significantly upregulated in patients with liver cancer, while they were downregulated by CTD treatment in HCC cells." (PMID 38017425, 2023). "Among them, TOP2A, CENPF, MEFV and C9orf72 directly affect the prognosis of patients with liver cancer." (PMID 38017425, 2023). "In order to verify the expression of TOP2A in HCC, we selected the expression of these three antibodies in normal tissues and liver cancer tissues." (PMID 35033076, 2022). "Subsequent validation suggested TOP2A, RRM2, NEK2, CDK1, and CCNB1 as the prognostic biomarkers of liver cancer." (PMID 34681056, 2021).
liver cancer (continued). "Our results suggest the potential use of TOP2A, RRM2, NEK2, CDK1, and CCNB1 as prognostic biomarkers in liver cancer." (PMID 34681056, 2021). "miR-144-3p functions in liver cancer cell proliferation, motility, infiltration, and EMT pathways by modulating TOP2A, which may be considered a potential target for liver anticancer therapy." (PMID 38806610, 2024). "DNA topoisomerase II alpha (TOP2A) and ribonucleotide reductase regulatory subunit M2 (RRM2) were discovered to be the most significant in PPI network analysis and survival analysis in liver cancer and for PCa." (PMID 35409038, 2022). "And for HOW TOP2A regulates the process of liver cancer this paper is not clear, the next step we intend to find TOP2A gene regulation of liver cancer control axis, to find out its regulatory mechanism." (PMID 35033076, 2022). "The results revealed DNA topoisomerase II alpha (TOP2A), ribonucleotide reductase regulatory subunit M2 (RRM2), never in mitosis-related kinase 2 (NEK2), cyclin-dependent kinase 1 (CDK1), and cyclin B1 (CCNB1) as the hub genes for liver cancer." (PMID 34681056, 2021). "In addition to CCNB1, CDK1, CDC45, BUB1B, and CCNA2, we also identified five hub genes in Chinese liver cancer, namely AURKA, KIF11, TOP2A, TPX2, and HMMR, which play a crucial role in regulating the cell cycle." (PMID 34257537, 2021). "TOP1 and TOP2A are key tumor drivers in liver cancer 24, suggesting that TOP1 and TOP2A might be promising targets for treating malignances." (PMID 31956371, 2020). "The top modular genes, TOP2A, CDC20, PRC1, CCNB2, and NUSAP1, were highly associated with HCC onset and development; high expression of TOP2A, CDC20, or CCNB2 was correlated with poor survival time in TCGA liver cancer patients, implying their potential as biopsy-based prognostic markers." (PMID 31001331, 2019). "Therefore, MAPT, TOP2A, CENPF and MEFV were identified as hub genes of CTD targets that regulate autophagy and also sever as oncogenes or tumour suppressor genes to affect the prognosis of patients with liver cancer." (PMID 38017425, 2023). "Interestingly, three of them (CCNB1, TOP2A, NEK2) were also identified as crucial genes in HCV-HCC, which might to some extent reflect the common transcriptome regulatory mechanisms in liver cancer induced by viral hepatitis." (PMID 33946043, 2021). "The mRNA sequences of 371 patients with TCGA liver cancer were analyzed by functional module method。As can be seen from the volcanic map, the number of genes with TOP2A showing significant positive correlation is higher than the number of genes with TOP2A showing significant negative correlation." (PMID 35033076, 2022). "The results showed that UBE2C, PTTG1, TOP2A and SPP1 were positive, FCN3, SLC22A1, ADH4, CYP2C8, SLC10A1, and FBP1 were negative in liver cancer tissues." (PMID 38664521, 2024).